ANKRD49 (ankyrin repeat domain 49)
Description:
Induces HBG1 expression. May have a role in spermatogenesis where it promotes autophagy in response to serum starvation, via the NF-kappaB pathway (By similarity).
Synonyms: FGIF; FLJ20189; GBIF
Tractability: No criterion of Open Targets' tractability assessment is met for any kind of drug.
Gene: Protein-coding gene on chromosome 11 (94,493,979 to 94,499,583, forward strand). Ensembl gene ENSG00000168876.
Subcellular location: Nucleus
Subcellular location (Human Protein Atlas): Nucleoli; Nucleoplasm; Golgi apparatus
Gene Ontology:
Molecular function: protein binding
Biological process: positive regulation of DNA-templated transcription
Cellular component: nucleus
Genetic constraint (gnomAD): Loss-of-function variants: 15 observed, 18.92 expected, observed/expected ratio (o/e) 0.79, 90% interval 0.53 to 1.22. The upper end of that interval is the gene's LOEUF score, 1.22, which puts it in group 5 of 6, group 1 being the genes least tolerant of losing a copy. Missense variants: 209 observed, 282.85 expected, observed/expected ratio (o/e) 0.74, 90% interval 0.66 to 0.83. Synonymous variants: 84 observed, 100.97 expected, observed/expected ratio (o/e) 0.83, 90% interval 0.7 to 1.
Homologues: Orthologues: chimpanzee ANKRD49 (99% identical), macaque ANKRD49 (99% identical), pig ANKRD49 (94% identical), dog ANKRD49 (93% identical), rabbit ANKRD49 (88% identical), mouse Ankrd49 (87% identical), rat Ankrd49 (85% identical), guinea pig ANKRD49 (67% identical), tropical clawed frog ankrd49 (64% identical), zebrafish ankrd49 (49% identical), Drosophila melanogaster Ankrd49 (34% identical), Caenorhabditis elegans F26F4.12 (31% identical).
Diseases named in the same sentence as ANKRD49 in open-access papers:
ANKRD49 is named in the same sentence as 10 diseases in open-access papers, as found by Europe PMC text mining. Sharing a sentence is not in itself a finding about the gene and the disease. The quoted sentences say what the papers report.
malignant glioma (3 papers, 2017 to 2023). A grade III or grade IV glioma arising from the central nervous system. "The ankyrin repeat domain 49 protein (ANKRD49) contains four ankyrin repeat motifs, and it is closely associated with the occurrence and development of malignant gliomas and gastric cancer." (PMID 35775112, 2022). "As an oncogene in malignant gliomas, ANKRD49 reduces cellular apoptosis and facilitates cell cycle progression to promote the proliferation of glioma cells." (PMID 37964204, 2023). "It has been documented that ANKRD49 is highly expressed in several carcinomas, including gastric cancer and malignant gliomas." (PMID 37964204, 2023). "In the present study, we investigated the clinical implication of ANKRD49 in glioma patients and the function of ANKRD49 in human malignant glioma cells U251 and U87." (PMID 28694302, 2017). "To gain deep insight into the functional role of ANKRD49 in malignant glioma progress, we utilized lentivirus-mediated shRNA to knockdown ANKRD49 expression in malignant glioma cells U251 and U87." (PMID 28694302, 2017). "Taken together, our findings implicate that ANKRD49 promotes the proliferation of human malignant glioma cells." (PMID 28694302, 2017). "To further explore the relationship between ANKRD49 and malignant glioma, we performed a clinical research in TCGA to study the expression pattern of ANKRD49 in LGG and GBM, two different malignant levels of glioma." (PMID 28694302, 2017). "ANKRD49 also participates in the progression of malignant gliomas and gastric cancer in humans." (PMID 37964204, 2023). "ANKRD49 can be an attractive therapeutic target for malignant glioma." (PMID 37964204, 2023). "Remarkable correlation between ANKRD49 and malignant glioma suggests that ANKRD49 may be involved in malignant glioma development and progression." (PMID 28694302, 2017). "ANKRD49 knockdown impaired the proliferation of U251 and U87 malignant glioma cells." (PMID 28694302, 2017). "In the present study, we also showed a decreased level of Chk1 phosphorylation, indicating that Chk1 may participate in the oncogenic function of ANKRD49 in malignant glioma cells." (PMID 28694302, 2017). "In conclusion, we identify ANKRD49 as an oncogene in malignant gliomas." (PMID 28694302, 2017). "ANKRD49 maybe an attractive target for malignant glioma therapy." (PMID 28694302, 2017). "Therefore, ANKRD49 may serve as a prognostic factor and a potential therapeutic target in human malignant glioma." (PMID 28694302, 2017). "Therefore, whether ANKRD49 could regulate autophagy of malignant glioma cells needs further studies." (PMID 28694302, 2017).
glioma (2 papers, 2017 to 2023). A benign or malignant brain and spinal cord tumor that arises from glial cells (astrocytes, oligodendrocytes, ependymal cells). "Therefore, we concluded that ANKRD49 is overexpressed in human glioma tissues, and high expression of ANKRD49 is significantly associated with high disease grade and poor survival." (PMID 28694302, 2017). "We showed that ANKRD49 expression is positively correlated to glioma malignancy and accordingly has adverse impacts on overall survival rate." (PMID 28694302, 2017). "Here, in the present study, we found that the expression of ANKRD49 in human glioma is significantly increased in comparison with normal donors." (PMID 28694302, 2017). "Through reanalyzing RNA sequencing data of glioma-related datasets in TCGA database, we found that the expression of ANKRD49 was predominantly higher in glioma samples compared with matched normal samples (fold change =2.11, P=2.99E-09)." (PMID 28694302, 2017). "Mining through The Cancer Genome Atlas (TCGA) database, we found that the expression of ANKRD49 was increased in glioma tissues and that high expression of ANKRD49 was strongly associated with high disease grade and poor overall survival." (PMID 28694302, 2017). "High expression of ANKRD49 is correlated with high disease grade and poor overall survival in glioma patients." (PMID 28694302, 2017). "In contrast with LGG, most GBM cases expressed high level of ANKRD49 (P<0.001), indicating that the expression of ANKRD49 is positively related to the malignant level of glioma." (PMID 28694302, 2017). "As expected, ANKRD49 was found to be expressed in four human glioma cell lines." (PMID 28694302, 2017). "Here, we showed that ANKRD49 expression is positively related to glioma grade and manifests a significant prognosis difference between glioma samples and non-glioma samples, suggesting that ANKRD49 may be a prognosis predictor." (PMID 28694302, 2017). "Therefore, ANKRD49 knockdown promotes the apoptosis of glioma cells." (PMID 28694302, 2017). "However, the role of ANKRD49 in glioma remains largely unclear." (PMID 28694302, 2017). "However, the function of ANKRD49 in human glioma remains elusive." (PMID 28694302, 2017). "Interestingly, a recent study demonstrated that ANKRD49 expression is positively correlated to glioma grade and manifests a significant prognosis difference between glioma samples and non-glioma samples, suggesting that ANKRD49 may serve as a prognosis predictor." (PMID 37964204, 2023).
lung adenocarcinoma (2 papers, 2022 to 2023). A carcinoma that arises from the lung and is characterized by the presence of malignant glandular epithelial cells. "ANKRD49 has been demonstrated to promote the invasion and metastasis of A549 cells, a lung adenocarcinoma cell line, via activating the p38/ATF-2 signaling pathway and then elevating the levels of MMP2/MMP9 in our previous study." (PMID 37964204, 2023). "Ankyrin repeat domain 49 (ANKRD49) has been found to be highly expressed in multiple cancer including lung adenocarcinoma (LUAD) and lung squamous carcinoma (LUSC)." (PMID 37964204, 2023). "To further explore the role of ANKRD49 in LUAD, we employed a lung adenocarcinoma A549 cell line to create stable ANKRD49 overexpression or downregulated A549 cells." (PMID 35775112, 2022). "The median H‐score of ANKRD49 expression in lung adenocarcinoma tissues was 224.5 (29.0 ~ 300), and it was 22.0 (0 ~ 138) in the adjacent non‐tumorous tissues." (PMID 35775112, 2022). "Our results also show that ANKRD49 can promote the invasion and migration of A549 cells via a P38 MAPK/ATF‐2/MMPs signalling pathway in vitro and in vivo, suggesting a novel target for the remedy of lung adenocarcinoma." (PMID 35775112, 2022). "Positive ANKRD49 immunoreactivities were detected in lung adenocarcinoma tissues (Figure 1Ab‐d), but not in their adjacent non‐tumorous tissues." (PMID 35775112, 2022).
lymph node metastasis (2 papers, 2022 to 2023). "Our Spearman correlation analysis further revealed a positive relationship between the level of ANKRD49 expression and advanced LUAD developments, including clinical TNM stage, lymph node metastasis, distal metastasis, and differentiation." (PMID 35775112, 2022). "Spearman's interrelated analysis showed that positive expression of ANKRD49 correlated well with TNM stage, lymph node metastasis, distant metastasis, and differentiation at high correlation coefficients of 0.617, 0.385, 0.592, and 0.507, respectively." (PMID 35775112, 2022). "Our Cox modelling also suggested that high level of ANKRD49 expression may be used as an independent prognostic factor for patients with LUAD and their rate of survival, in particular at advanced disease stages, including TNM stage (III‐IV), lymph node metastasis, and differentiation." (PMID 35775112, 2022).
non-small cell lung carcinoma (2 papers, 2017 to 2023). A group of at least three distinct histological types of lung cancer, including non-small cell squamous cell carcinoma, adenocarcinoma, and large cell carcinoma. "In human patients of non-small-cell lung cancer, ANKRD49 serves as an invasion-associated gene and predicts patients’ survival." (PMID 28694302, 2017). "Similar results from a previous study showing ANKRD49, as one of the four gene signature from NCI-60 cell line, had a strong prediction value for non-small-cell lung cancer." (PMID 37964204, 2023). "Similar results from a previous study showed that ANKRD49, as one of the four gene signature from NCI-60 cell line, had a strong prediction in non-small-cell lung cancer." (PMID 28694302, 2017).
lung carcinoma (1 paper, 2022). "The ANKRD49 gene has also been detected as an invasion‐associated gene from microarray databases of the NCI‐60 lung cancer cell line." (PMID 35775112, 2022).
metastasis (1 paper, 2023). The spread or migration of cancer cells from one part of the body (where they first appeared) to another. "Similar results from our previous study showed that ANKRD49 protein in LUSC was elevated and correlated positively with the tumor node-metastasis stage, lymph node metastasis, distal metastasis, and differentiation." (PMID 37964204, 2023).
cancer (3 papers, 2017 to 2023). A tumor composed of atypical neoplastic, often pleomorphic cells that invade other tissues. "Furthermore, we utilized lentivirus-mediated shRNA, a loss-of-function strategy, to downregulate ANKRD49 expression in H1299 and H1703 cells (a LUSC cell line), and discovered that knockdown of ANKRD49 suppressed the invasion and migration of these cancer cells." (PMID 37964204, 2023). "Ankyrin repeat domain 49 protein (ANKRD49) is highly expressed in several carcinomas; however, its pattern of expression and role in LUAD are not known." (PMID 35775112, 2022).
tumor (2 papers, 2022 to 2023). "The data showed that the expression of ANKRD49 mRNA in tumor tissues was significantly higher than that in adjacent normal tissues." (PMID 37964204, 2023). "In consideration of different subtypes of NSCLC as well as heterogeneity of tumor cells, the function of ANKRD49 in NSCLC progression need further clarification." (PMID 37964204, 2023). "Nevertheless, the distribution of tumor cells in the lung tissues of mice injected with ANKRD49-sh or LV3 showed the opposite trend." (PMID 37964204, 2023). "HE staining also illustrated that more tumor cells appeared in perivascular and peribronchial regions in lung tissues from mice injected with ANKRD49-OE H1299 cells than in control mice." (PMID 37964204, 2023). "Correlation analysis displayed that the metastatic rates of the tumor cells were positively correlated with the expression of ANKRD49, MMP-2, MMP-9, p-JNK, p-c-Jun or p-ATF2." (PMID 37964204, 2023). "Considering the heterogeneity of tumor cells, the function and mechanism of ANKRD49 in NSCLC need more NSCLC-originated cells to clarify." (PMID 37964204, 2023). "HE staining of lung sections showed that the distribution of A549 tumour cells were mostly around the airway, and more cell invasions were seen in the ANKRD49 OE group." (PMID 35775112, 2022). "To explore the potential molecular mechanisms of ANKRD49 in LUAD invasion and migration, we examined some of the key players associated with tumour metastasis." (PMID 35775112, 2022). "Of course, apart from MMPs and MAPKs, other mechanisms such as epithelial-to-mesenchymal transition (EMT), angiogenesis or the stemness of tumor cells may be invovled in ANKRD49’s function on migration and invasion of NSCLC cells." (PMID 37964204, 2023). "No statistical differences were found between the levels of ANKRD49 expression and sexes (p = 0.102), ages (p = 0.214), histological grades (p = 0.185), or tumour sizes (p = 0.124)." (PMID 35775112, 2022).
ANKRD49 also shares sentences with these, for which no sentence is quoted: gastric cancer (2 papers).